TNF (tumor necrosis factor)
Diseases named in the same sentence as TNF in open-access papers (continued):
Sharing a sentence is not in itself a finding about the gene and the disease.
metastatic prostate carcinoma (6 papers, 2004 to 2025). A carcinoma that arises from the prostate gland and has spread to other anatomic sites. "When patients with metastatic prostate cancer were compared with both groups of patients with localised prostate cancer, there were significant differences in IL-6 and TNF-α levels among the groups." (PMID 15150588, 2004). "In conclusion, viewed in the context of similar observations made for other cancers, these data further support a relationship between elevated IL-6 and TNF-α levels and metastatic prostate cancer." (PMID 15150588, 2004). "This pathway comprises the tumor necrosis factor- (TNF) and FAS receptor signaling pathways and seems to be particularly dysregulated in androgen-independent metastatic prostate cancer compared with localized primary prostatic tumors." (PMID 23185449, 2012). "TNF-α is a key mediator of inflammation; studies have demonstrated that serum TNFα is elevated in patients with metastatic prostate cancer, further serum TNF-α activity was positive in 76% of patients with relapsed disease and patients with elevated TNF-α has a higher mortality rate." (PMID 33076397, 2020). "As expected, the FAS receptor signaling pathway appeared to be significantly affected in metastatic prostate cancer and during disease recurrence, but neither the Fas receptor- nor the TNF-α signaling pathway were found to be significantly dysregulated in androgen-independent prostate cancer." (PMID 23185449, 2012).
muscle disorders (6 papers, 2012 to 2022). "TNF-α is an inflammatory cell chemokine that generally has a high expression level in chronic diseases or muscle disorders; high levels of TNF-α can cause muscle atrophy." (PMID 36078046, 2022). "TNF-α levels are increased during muscle wasting and chronic muscle degeneration and regeneration processes, which are characteristic for primary muscle disorders." (PMID 26447881, 2015).
myasthenia gravis (6 papers, 2010 to 2026). Myasthenia gravis (MG) is a rare, clinically heterogeneous, autoimmune disorder of the neuromuscular junction characterized by fatigable weakness of voluntary muscles. "Further studies affirm this observation, indicating a significant role of inflammatory markers such as IL-6 and TNF-α in the decline of muscle strength and the onset of myasthenia gravis." (PMID 37789429, 2023). "The associated targets of SGR in the treatment of myasthenia gravis have been shown to focus primarily on the PI3K-Akt signaling pathway, the TNF-α and IL-17 signaling pathways, and Th17 cell differentiation, which are conventional pathways for the pathogenesis and development of myasthenia gravis." (PMID 36290632, 2022). "In myasthenia gravis (MG), miR-146a is downregulated and negatively correlated with levels of messenger RNA (mRNA) such as interleukin-1 receptor-related kinase 1 (IRAK1), tumor necrosis factor (TNF) receptor-related factor 6 (TRAF6), and inducible T cell costimulator factor (ICOS)." (PMID 38058356, 2023).
myeloid malignancies (6 papers, 2017 to 2024). "TNF can activate the canonical NFκB pathway, which is associated with myeloproliferation, both in myeloid neoplasms and in “stress” or “emergency” hematopoiesis following a hematopoietic insult such as the systemic inflammation resulting from an infection." (PMID 34140953, 2021). "Inflammation and TNF signaling have also been directly implicated in the disruption of BM microenvironment and hematopoiesis in patients with a range of myeloid malignancies, including elevated TNF levels in patients with AML, correlating with high leukocyte count and resistant disease." (PMID 28637883, 2017). "In keeping with these clinical findings, miR-146a KO mice have been shown to develop increased levels of pro-inflammatory cytokines such as IL-6 and TNFα and develop a myeloid malignancy that significantly reduces their lifespan." (PMID 36505238, 2022). "However, using myeloid tumor cells (THP1) or HLA-I-deficient B-lymphoblastoid cells (721.221) as target cells, we observed a similar enhancement of IFN-γ, TNF or CD107a expression induced by IAV, 3p-dsRNA or pre-incubation with IFN-α." (PMID 37569596, 2023).
Myelopathy (6 papers, 2013 to 2024). Myelopathy is an descriptive term, referring to pathology leading to a neurologic deficit related to the spinal cord. "HTLV-1-infected individuals may develop a neurologic inflammatory condition known as HTLV-1-associated myelopathy (HAM/TSP), in which the high production of TNF is observed." (PMID 36311773, 2022). "Moreover, TNF was identified as a key cytokine linked to MMP-9 production by PBMCs in HTLV-1-infected patients regardless of myelopathy." (PMID 36311773, 2022).
myonecrosis (6 papers, 2018 to 2025). "Initiation of myonecrosis triggers a complex inflammatory-immune response, with the production of cytokines (such as TNF-α, TGF-β, interleukin-6 and interleukin-1) and breakdown of the extracellular matrix that attracts neutrophils and macrophages to the site of damage." (PMID 40275384, 2025). "In addition, erythromycin pretreatment reportedly reduced tumor necrosis factor-α release from activated neutrophils in a C. perfringens gas gangrene mouse model." (PMID 35312893, 2022). "In the last experimental period examined (Day 7), the amount of myonecrosis, number of inflammatory cells, CD68+ (M1) and CD206+ (M2) macrophages as well as the expression of IL‐6, TNF‐α and TGF‐β mRNA were lower compared with previous periods (Day 2 and 4)." (PMID 30024093, 2018). "The information given by hsTnT, and TNF and DAS28-ESR in our study might be relevant in myonecrosis and inflammation that are thought to be involved in the pathogenesis of CHD." (PMID 36763689, 2023).
nematode infection (6 papers, 2015 to 2024). "Finally, elevated resistin was associated with higher concentration of IL-6, CCL2 and TNFα and inflammatory factors, suggesting that the resistin/proinflammatory cytokine immune axis we identified in mice is also present in human nematode infections." (PMID 25568944, 2015). "TNF triggers an inflammatory, Th-1 type immune response that is usually suppressed by nematode infections, which may explain our results." (PMID 36693052, 2023).
Optic neuropathy (6 papers, 2009 to 2024). "In conclusion, tacrolimus may protect against axon loss in TNF-induced optic neuropathy by inhibiting the CaN/NFATc1 pathway." (PMID 31087207, 2019). "Recently, 15 cases of anti-TNF-α-associated optic neuropathy were reported, the effects of anti-TNF-α therapy may be related to changes in the balance of immunologic homeostasis." (PMID 19490629, 2009). "The inflammatory cytokine TNF-α seems to be playing a major role in the triggering of optic neuropathy after acute traumatic events in the eye." (PMID 37803488, 2024). "Experimental studies in various disease models addressed mechanisms of action and indicated modulation of neurotrophic factors (IGF-1, BDNF, CNTF, FGF-2, TNF-α) and immunomodulators (IL-10, IL-6, COX-2, NF-κB) by electrical stimulation of the eye in optic neuropathies." (PMID 35361287, 2022).
oropharyngeal carcinoma (6 papers, 2016 to 2024). Carcinoma, predominantly squamous cell, arising from the epithelial cells of the oropharynx. "Further studies from our country have talked about other markers in oropharyngeal cancer, such as TNF- α, blood group type association, MicroRNA-486-5p and MicroRNA-10b-5p, as well as the use of micro-Raman and FT-IR spectra of saliva." (PMID 38473308, 2024). "The concentrations of IL-17A, IL-17F, IL-17E/IL-25, and TNF-α in saliva samples in the patients diagnosed with oral and oropharyngeal cancer was correlated with the disease stage as well as with T, N, and M parameters separately." (PMID 32855976, 2020). "The aim of this study was to assess the levels of IL-17 and TNF-α in the saliva of patients with oral and oropharyngeal cancer." (PMID 32855976, 2020). "The aim of this study was to assess levels of IL-17A, IL-17E/IL-25, IL-17F, and TNF-α in the saliva in patients with oral and oropharyngeal cancer, depending on the degree of malignancy and bacteriological cultures from the oral cavity as potential biomarkers of cancer." (PMID 32855976, 2020). "The aim of this study was the analysis of the serum and salivary levels of IL-10, TNF-α, TGF-β and VEGF in patients with oropharyngeal cancer and in healthy individuals." (PMID 27547238, 2016). "Another clinical study of AXAL in previously untreated, surgically resectable, stage II–IV oropharyngeal cancer found increased interferon gamma (IFN-g), tumor necrosis factor alpha (TNF-a), and tumor-infiltrating T cells after receiving the vaccine before and after surgery (NCT02002182)." (PMID 35008197, 2021). "Therefore, the aim of this study was to analyze the serum and salivary levels of IL-10, TNF-α, TGF-β and VEGF in patients with oropharyngeal cancer compared to healthy individuals." (PMID 27547238, 2016).
overactive bladder (6 papers, 2013 to 2026). Symptom of overactive detrusor muscle of the urinary bladder that contracts with abnormally high frequency and urgency. "Patients with an overactive bladder (OAB) have been found to have increased mRNA levels of some urine biomarkers associated with inflammation (such as TNFα, IL2, NGF)." (PMID 41596750, 2026). "Increased responsive proinflammatory mediators (NGF, ICAM-1, COX-2, IL-1β, IL-6, TNF-α) likely contribute to bladder overactivity." (PMID 39941129, 2025). "As TNF-α is increased in overactive bladder as well as IC/BPS, measurements of TNF-α concentration on their own will be unlikely to produce a stand-alone clinical test for IC/BPS." (PMID 35193610, 2022). "The oxidative stress markers and proinflammatory cytokines including IL-8-like cytokine CXCL1/CINC-1, TNF-α, and IL-6 were significantly higher in the atherosclerotic ischemic rats; these markers could be key factors in the development of bladder overactivity." (PMID 24098552, 2013). "Most research, including our own previous investigations, suggests that individuals with overactive bladder (OAB) exhibit increased concentrations of inflammatory biomarkers in their serum or urine, such as TNF-α." (PMID 39684342, 2024).
periventricular leukomalacia (6 papers, 2012 to 2025). Periventricular leukomalacia (PVL) is a brain injury disorder characterized by the death of the white matter of the brain due to softening of the brain tissue. "Autopsy studies of periventricular leukomalacia have shown enhanced TNF-α expression in cortical neurons and that pre-myelinating oligodendrocytes are the major apoptotic cells in the white matter." (PMID 25540015, 2014). "Furthermore, increased TNF expression has been detected throughout white and gray matter regions in preterm infants with periventricular leukomalacia." (PMID 32293473, 2020). "The involvement of astrocytes in the pathogenesis of WMI is suggested by increased cytokine expression (IL-1β, IL-6, and TNF-α) in both the diffuse and focal components of periventricular leukomalacia (PVL)." (PMID 22530124, 2012). "TNF-α exerts its biologic effects by signaling through two receptors, the TNF receptor (TNFR) 1 and TNFR2, which are detected in affected brain areas in preterm infants with periventricular leukomalacia." (PMID 25540015, 2014).
proliferative vitreoretinopathy (6 papers, 2012 to 2026). Vitreoretinal membrane shrinkage or contraction secondary to the proliferation of primarily retinal pigment epithelial cells and glial cells, particularly fibrous astrocytes, followed by membrane formation. "TNFα was found in 22 of 26 epiretinal membranes of patients with proliferative vitreoretinopathy, with positive TNFα staining both intracellularly and in the extracellular matrix." (PMID 23049173, 2012).
prostate adenocarcinoma (6 papers, 2017 to 2023). "Moreover, deletion of GPR54 or ERK5 in PSMA‐CAR‐T cells increased the cytotoxicity of PSMA‐overexpressing PC3 cells (human prostate adenocarcinoma cells) at a low effector‐to‐target ratio, as well as TNFα release at an effector‐to‐target ratio of 1:1." (PMID 35224894, 2022).
prostatic hyperplasia (6 papers, 2018 to 2025). "The biorepository provided transition zone tissues from patients taking TNF-antagonists who also underwent surgery for prostatic diseases (n = 5)." (PMID 35440548, 2022).
Pyoderma (6 papers, 2020 to 2026). Any manifestation of a skin disease associated with the production of pus. "Dogs’ pyoderma treated with A. vera gel ointment had low haptoglobin and tumor necrosis factor-α concentrations than gentamicin." (PMID 38667017, 2024). "Dogs’ pyoderma treated with A. vera 20% and 40% were more likely to have low HP and TNF-α concentrations than gentamicin ([OR=4.6; 95% CI=1.31-17.40; p<0.05]; [OR=5.2; 95% CI=1.04-22.30; p<0.05]), respectively, as shown in Table-6." (PMID 33363329, 2020). "In a murine pyoderma model, bentonite pre-treatment of S. pseudintermedius prevented lesion development, reduced bacterial burden, and downregulated cutaneous expression of TNFα, IL-1β, and IL-13, findings that were corroborated by histological improvements." (PMID 41576001, 2026). "Dogs’ pyoderma treated with A. vera gel ointment 20% and 40% were more likely to have low haptoglobin and tumor necrosis factor-α concentrations than gentamicin 1% ([odds ratio [OR]=4.6; 95% confidence interval [CI]=1.31-17.40; p<0.05]; [OR=5.2; 95% CI=1.04-22.30; p<0.05]), respectively." (PMID 33363329, 2020). "TNFα inhibitors could be considered in APLAID patient with gangrenous pyoderma." (PMID 34093563, 2021).
Respiratory syncytial virus infection (6 papers, 2013 to 2025). "Respiratory syncytial virus infection generates intense neutrophilic infiltration, release of IL-6, IL-8, TNF-α, and proteolytic enzymes, contributing to epithelial fragility." (PMID 41459355, 2025). "In Sendai virus and respiratory syncytial virus infections, high intracellular levels of DVGs protect infected cells from death by altering the outcome of the mitochondrial antiviral signaling-mediated tumor necrosis factor response." (PMID 36069441, 2022). "Respiratory syncytial virus infection increases Mif MRNA expression in mouse macrophages and inhibition of MIF with ISO-1 (small molecule inhibitor) inhibits RSV-induced release of TNF, MCP-1 and IL-10." (PMID 36110852, 2022). "Previous studies have observed that type I IFNs inhibit TNF-α-dependent MMP-9 activation in tumour cell lines, and IFN therapy can suppress MMP expression in tumour models and during respiratory syncytial virus infection in mice." (PMID 35512020, 2022). "Other studies have indicated that TNF-α may be a major cytokine that plays a protective role as part of the host response especially in acute viral myocarditis, hepatitis B virus (HBV), and respiratory syncytial virus infection." (PMID 38060612, 2023).
rotator cuff tear (6 papers, 2020 to 2025). "Serum TNF-α levels are elevated in patients with rotator cuff tears and correlate with sleep disturbance, suggesting that systemic inflammatory burden contributes to symptom severity." (PMID 40688916, 2025). "This partially contradicts the findings of others, showing a rather increased expression of pro-inflammatory factors like SDF1, IL-1β, TNF-α or IL-6 in the bursae of patients with a rotator cuff tear or frozen shoulders." (PMID 38201221, 2023). "Likewise, clinical specimens from patients with rotator cuff tears exhibit upregulation of TNF-α, IL-1β, and IL-6 in the subacromial bursa, implicating these cytokines in pain generation and chronic inflammation inflammatory cytokine." (PMID 40728980, 2025). "Together, these findings indicate that, following rotator cuff tear, an early TNF-α-driven increase in NTN4 may serve as a key intermediary that prolongs MMP-3-mediated matrix degradation, thereby linking acute inflammation to sustained tendon remodeling." (PMID 40688916, 2025). "The authors found significantly elevated levels of IL-1β, IL-6, tumor necrosis factor (TNF-α), inducible nitric oxide synthase (iNOS), cyclooxygenase-2 (COX-2), and vascular endothelial growth factor (VEGF) in synovial tissue of shoulders with full-thickness rotator cuff tears." (PMID 32821573, 2020).
rubella (6 papers, 2010 to 2023). A viral infection caused by the rubella virus. "One study investigated the specific antibody responses against measles and rubella after a minimum of one dose of MMR in 50 children with JARD (46 children with JIA) on MTX or MTX plus anti-TNF-alpha blockers and 31 healthy children." (PMID 34936010, 2022). "Since cytokines are important for the development and shaping of innate and adaptive immune responses to rubella, we examined associations between extended haplotypes and rubella virus-specific cytokine (IFN-γ, IL-2, IL-6, TNF-α, and GM-CSF) secretion levels." (PMID 20668555, 2010). "We analyzed extended SNP-defined LTA, TNF, LST1, and HLA haplotype profiles and examined their contribution to humoral and cellular immune responses following the recommended two doses of the US licensed rubella-containing vaccine." (PMID 20668555, 2010).
schwannoma (6 papers, 2020 to 2025). A benign, usually encapsulated slow growing tumor composed of Schwann cells. "Cellular inflammation and damage were induced by in vitro applying 20 μg/ml LPS or 10 ng/ml TNFα to rat schwannoma RT4 cells." (PMID 40069892, 2025). "A mouse study identified one of the secretory factors from the poor-hearing ears (with schwannomas) as TNFα." (PMID 41300330, 2025). "MMP9, produced by schwannoma cells, promotes schwannoma invasion in response to TNF-α and can be inhibited by targeting the eukaryotic translation initiation factor complex, eIF4F." (PMID 38887507, 2024). "TNF-α stimulation of schwannoma cells increased the number of invading cells by over 100-fold without affecting viability (P < .0002) compared to Schwann cells." (PMID 38887507, 2024). "We first confirmed the expression of TNF-α in an established human schwannoma cell line (HEI-193) and primary VS cultures established from freshly resected tumor specimens." (PMID 38914647, 2024). "Human schwannoma cells secreted MMP9 in response to TNF-α which promoted cellular invasion and adhesion protein expression in vitro." (PMID 38887507, 2024). "Taken together, we have demonstrated that TNF-α is actively secreted by schwannoma cells which may then upregulate HAS expression and modulate hyaluronan deposition." (PMID 38914647, 2024).
Sensory neuropathy (6 papers, 2011 to 2023). Peripheral neuropathy affecting the sensory nerves. "In the context of chemotherapy-induced sensory neuropathy, pro-inflammatory cytokines such as interleukin-6 (IL-6) or tumor necrosis factor-α (TNF-α) appear to be of particular relevance." (PMID 31969555, 2020). "The results above suggest that spinal TNFα plays a role in the gp120 application-induced sensory neuropathy." (PMID 21599974, 2011). "In line with this concept, in the present study, diabetic mice presented enhanced levels of IL-1β and TNF-α in the spinal cord, while MSC treatment inhibited this upregulation, in parallel with its effects on behavioral sensory neuropathy." (PMID 29933760, 2018). "Evidence shows that painful HIV sensory neuropathy is influenced by neuroinflammatory events that include the proinflammatory molecules, MAP Kinase, tumor necrosis factor-α (TNFα), stromal cell-derived factor 1-α (SDF1α), and C-X-C chemokine receptor type 4 (CXCR4)." (PMID 25078297, 2014).